ZFAS1 (ZNFX1 antisense RNA 1)
Diseases named in the same sentence as ZFAS1 in open-access papers (continued):
Sharing a sentence is not in itself a finding about the gene and the disease.
infection (2 papers, 2025). The state of being infected such as from the introduction of a foreign agent such as serum, vaccine, antigenic substance or organism. "Zfas1 has been shown to positively regulate the antiviral innate immune response during infection with vesicular stomatitis virus (VSV) and herpes simplex virus type 1 (HSV–1)." (PMID 41214723, 2025). "Silencing of IRF1AS1 or ZFAS1 promoted influenza virus replication, while knockdown of PSMB8-AS1 or LGALS17A demonstrated inhibitory effects during the late infection stage." (PMID 40626712, 2025).
degenerative disease (1 paper, 2022). "Collectively, our study is the first to show the functional epigenic regulation of the ZFAS1/miR-4711-5p/AAK1 axis in cell apoptosis and ECM degradation under the IDD condition, which may provide new understanding of the pathogenesis of degenerative disease." (PMID 36561842, 2022).
hematologic malignancies (1 paper, 2025). "Our findings align with prior reports highlighting ZFAS1’s involvement in other hematologic malignancies and solid tumors." (PMID 40697388, 2025).
neurological diseases (1 paper, 2025). "Notably, ZFAS1 emerged as a significantly interactive lncRNA, demonstrating regulation of microglia-mediated inflammation and representing a promising therapeutic target for modulating neuroinflammation in virus-associated neurological diseases." (PMID 41214723, 2025). "Knockdown of ZFAS1 modulated microglia-driven inflammation without altering viral replication, underscoring its potential as a therapeutic target for mitigating neuroinflammation in virus-associated neurological diseases." (PMID 41214723, 2025).
ZFAS1 also shares sentences with these, for which no sentence is quoted: acute myocardial infarction (5 papers); acute myeloid leukemia (4); lung adenocarcinoma (3); clear cell renal cell carcinoma (2); hepatitis B (2); acute promyelocytic leukemia (1); breast ductal carcinoma (1); Burkitt lymphoma (1); cardia cancer (1); chronic kidney disease (1); chronic myeloid leukemia (1); Cockayne syndrome (1); colorectal adenocarcinoma (1); digestive system cancer (1); digestive system tumors (1); glioblastoma (1); head and neck cancer (1); heart failure (1); HIV-1 infection (1); Hypertension (1); intestinal cancer (1); liver disease (1); lung squamous cell carcinoma (1); metastasis (1); Nephroblastoma (1); Obesity (1); oesophageal adenocarcinoma (1); oligodendroglioma (1); oral squamous cell carcinoma (1); osteoporosis (1).
A further 8 diseases each share a sentence with ZFAS1 in 1 paper.